NEDD9 (neural precursor cell expressed, developmentally down-regulated 9)
Diseases named in the same sentence as NEDD9 in open-access papers (continued):
Sharing a sentence is not in itself a finding about the gene and the disease.
gastric cancer (continued). "In the present work, we observed that NEDD9 bound directly to MICAL1 in gastric cancer cells and this interaction increased under hypoxic condition." (PMID 31019460, 2019). "In all, it is concluded that MICAL1 is regulated by NEDD9 that facilitates hypoxia-induced gastric cancer cell migration via Rac1-dependent manner." (PMID 31019460, 2019). "This, along with the fact that NEDD9 is highly expressed in gastric cancer tissue compared to healthy tissue (92.5 vs. 7.5%) indicates that NEDD9 could potentially serve as target for future therapy strategies in gastric cancer." (PMID 33485292, 2021). "In summary, our findings suggest that increased expression of both epithelial and stromal NEDD9 and epithelial Cx43 could potentially be used as prognostic gastric cancer biomarkers." (PMID 33485292, 2021). "The result suggests a possibility that the upregulation of NEDD9 may contribute to the MICAL1 expression in gastric cancer cells." (PMID 31019460, 2019). "Aims and Hypothesis: NEDD9 is highly expressed in gastric cancer and has a significant involvement in its pathogenesis." (PMID 31019460, 2019). "Collectively, these results revealed that NEDD9/MICAL1 may act on Rac1 to affect hypoxia-induced gastric cancer cell migration." (PMID 31019460, 2019). "In contrast, MICAL1 deletion inhibited NEDD9-mediated migration in gastric cancer cell lines." (PMID 31019460, 2019). "Rac1 activation was increased in NEDD9-overexpressed gastric cancer cells." (PMID 31019460, 2019). "The functional resemblance of Nedd9 to Nedd4-1 in gastric cancer metastasis may be yielded from a connected biochemical process." (PMID 25395181, 2014). "However, involvement of NEDD9 with gastric cancer cell motility and relative mechanisms under hypoxic condition is still unknown." (PMID 31019460, 2019). "Furthermore, we observed that hypoxia stimulated Rac1 activation, which may serve as an important mediator for NEDD9/MICAL1-facilitated gastric cancer cell migration." (PMID 31019460, 2019). "However, the mechanism underlying the effect of NEDD9 on gastric cancer cell motility has not been fully investigated." (PMID 31019460, 2019). "Thus, Nedd9 is proposed as a prognostic biomarker for gastric cancer." (PMID 25395181, 2014). "Multivariate analysis found expression of NEDD9 and FAK as independent prognostic indicators for gastric cancer." (PMID 33485292, 2021). "So it is interesting to investigate the role of NEDD9 and MICAL1 in hypoxia-treated gastric cancer cells." (PMID 31019460, 2019). "In all, we identified a novel link between NEDD9 and MICAL1 in accelerating gastric cancer cell motility under hypoxia." (PMID 31019460, 2019). "Based on the finding that NEDD9 interacts with MICAL1 by far western screening, we further investigated whether MICAL1 was also involved in hypoxia-stimulated gastric cancer cell migration." (PMID 31019460, 2019). "However, least data are available about the relationship between NEDD9 and MICAL1 in gastric cancer cells." (PMID 31019460, 2019). "Therefore, it was identified that hypoxia-induced NEDD9 expression has the ability to maintain MICAL1 protein level by reducing its degradation, thereby maintaining gastric cancer cell migratory properties." (PMID 31019460, 2019). "Knockdown of NEDD9 significantly decreased the cell migration rate in both normoxia- or hypoxia-treated gastric cancer cells." (PMID 31019460, 2019). "Cancer tissue from 53 cases of node-negative and 55 cases of node-positive primary gastric carcinoma patients was analyzed for Cx43 and NEDD9 expression by immunohistochemical assay, and the results were correlated with the remaining clinical and pathological findings and survival." (PMID 33485292, 2021). "To further examine whether hypoxia stimulates gastric cancer cell migration in NEDD9-dependent manner, we investigated SGC-7901 and BGC-823 cell migration using wound closure assay after transfecting these cells with NEDD9 siRNA." (PMID 31019460, 2019).
gastric cancer (continued). "It is reported that NEDD9 overexpression correlates with poor prognosis of gastric cancer, However, in our study, due to the limited number of samples, we were unable to demonstrate the significant interaction between NEDD9, MICAL1, and gastric cancer progression (data not shown)." (PMID 31019460, 2019).
pancreatic cancer (6 papers, 2015 to 2023). "miR-125b, which was shown to be downregulated in pancreatic cancer and inhibits NEDD9 mRNA via PI3K/AKT signaling pathway, is associated with poor survival." (PMID 37686149, 2023). "In pancreatic cancer and hepatocellular carcinoma, NEDD9 was reported to be regulated by miR‐18a playing a key role during carcinogenesis." (PMID 34432355, 2021). "To explore the role of NEDD9 in the killing property of Baicalein on pancreatic cancer cells, we overepxressed NEDD9 in Baicalein-treated BxPC-3 or PANC-1 cells." (PMID 28915595, 2017). "In summary, we have identified NEDD9 as a novel target of Baicalein in two different types of pancreatic cancer cells." (PMID 28915595, 2017). "In this article, we systematically analyzed the effects of Baicalein on pancreatic cancer development, and explored the role of NEDD9 in Baicalein-affected cell signaling pathways." (PMID 28915595, 2017). "To determine the effects of NEDD9 on Akt and ERK signal pathways in pancreatic cancer cells, we blocked its expression by two synthesized NEDD9 siRNAs." (PMID 28915595, 2017). "miR-1252-5p, which was shown to be downregulated in pancreatic cancer and inhibits NEDD9 mRNA." (PMID 37686149, 2023). "However, there is so far limited information on NEDD9 as a drug target in pancreatic cancer treatment." (PMID 28915595, 2017). "Additionally, it was identified that miR-145 is inversely correlated with NEDD9 expression in pancreatic cancer tissues and that restoration of miR-145 in Panc-1 cells reduced NEDD9 mRNA and protein expression accompanied by inhibition of cell proliferation, invasion and migration." (PMID 25646678, 2015). "Through suppressing NEDD9 expression, Baicalein is able to inactivate the Akt and ERK cascades and thus effectively inhibit pancreatic cancer proliferation and invasion." (PMID 28915595, 2017). "Considering that NEDD9, which is involved in multiple Ras-related signalings including Akt and ERK, is highly expressed in pancreatic cancer tissues, we hypothesized that Baicalein may play a role on NEDD9 expression." (PMID 28915595, 2017). "Our research firstly demonstrated that Baicalein decreased phosphorylation of Akt at T-308 through targeting NEDD9-dependent PDK1 expression, but the target of Baicalein on the suppression of p-AKT at S-473 in pancreatic cancer cells requires further exploration." (PMID 28915595, 2017). "Thus, Baicalein may also decrease NEDD9 expression through repressing Wnt and/or TGF-β signal pathway and then suppress its downstream Akt and/or ERK activation in pancreatic cancer cells." (PMID 28915595, 2017). "It should be pointed out that although Baicalein significantly decreases NEDD9 expression to repress Akt and ERK signalings, NEDD9 might not be a direct target of Baicalein in pancreatic cancer cells." (PMID 28915595, 2017).
prostate carcinoma (6 papers, 2016 to 2025). A carcinoma that arises from epithelial cells of the prostate gland. "This genetic variant causes the overexpression of the NEDD9 gene, facilitating the onset and advancement of prostate cancer." (PMID 38970097, 2024). "An example of a genetic variation in the NEDD9 gene has been discovered, which is closely linked to a higher likelihood of developing prostate cancer in individuals of African population." (PMID 38970097, 2024). "Another study revealed that reduced expression of miR-451 increased chemoresistance in patients with metastatic castration-resistant prostate cancer by targeting NEDD9." (PMID 34314382, 2021). "This is complementary with our predictions, suggesting that after being regulated by KLF6, ZFP36 directly binds to NEDD9, thus acting as another novel upstream inhibitor of NFκB with a role in the amelioration of prostate cancer." (PMID 27078000, 2016). "After successful knockdown of NEDD9 by siRNA in the LAPC4 prostate cancer cell line, proliferation was significantly inhibited relative to control." (PMID 27078000, 2016). "A newly predicted interaction between NEDD9 and ZFP36 in particular was validated by co-immunoprecipitation, as was NEDD9's potential biological role in prostate cancer cell growth regulation." (PMID 27078000, 2016). "NEDD9 was also suggested to play a role specifically in prostate cancer cell proliferation." (PMID 27078000, 2016). "Our predicted NFκB pathway suggested 8 novel genes which were found to be highly down-regulated in lethal prostate cancer and highly functionally related to NFκB, namely ATF3, CXCL2, DUSP5, JUNB, NEDD9, SELE, TRIB1, and ZFP36." (PMID 27078000, 2016). "Notable genes in the predicted pathway included ATF3, JUNB, KLF6, NR4A2, ZFP36, DUSP5 and NEDD9, as well as STAT3 and IRF1 as novel upstream regulators, and SELE, CXCL1 and CXCL2 as novel downstream targets of NFκB in prostate cancer." (PMID 27078000, 2016).
hepatocellular carcinoma (5 papers, 2013 to 2024). A malignant tumor that arises from hepatocytes. "Overexpression of neural precursor cell expressed, developmentally downregulated 9 (NEDD9) is a prognostic marker of many cancers, including hepatocellular carcinoma (HCC)." (PMID 27974675, 2017). "Overexpressed NEDD9 could enhance the metastasis of hepatocellular carcinoma, while inhibition of NEDD9 could suppress the metastasis." (PMID 33344223, 2020).
lymph node metastasis (5 papers, 2013 to 2021). "We show that high expression of NEDD9 is significantly correlated with clinical staging, lymph node metastasis, histologic stage, and significantly shorter survival time." (PMID 34314382, 2021). "High NEDD9 expression was significantly correlated with advanced clinical stage, lymph node metastasis, and poor prognosis in PAC patients." (PMID 34314382, 2021). "High levels of expression of NEDD9 were significantly correlated with clinical staging, lymph node metastasis, and histological differentiation in PC patients." (PMID 30544746, 2018). "In our cohort of patients with lymph node metastases, we detected higher expression of epithelial Cx43 in the primary tumor and stromal Cx43 expression correlated with both epithelial NEDD9 (rho = 0.453) and stromal NEDD9 (rho = 0.484)." (PMID 33485292, 2021). "It was shown that higher NEDD9 levels were significantly correlated with clinical staging, lymph node metastasis and histological differentiation and patients with a higher NEDD9 expression had a significantly shorter survival time than those patients with lower NEDD9 expression." (PMID 30544746, 2018). "NEDD9 expression was significantly correlated with tumor invasion and differentiation, but not with other variables such as age, sex, TNM stage, or lymph node metastasis." (PMID 33710809, 2021).
Alzheimer disease (4 papers, 2013 to 2021). A progressive, neurodegenerative disease characterized by loss of function and death of nerve cells in several areas of the brain leading to loss of cognitive function such as memory and language. "NEDD9 has been associated with Alzheimer's disease, which has been recently claimed to share genetic risk factors with cholesterol levels." (PMID 23468652, 2013). "NEDD9 (neural precursor cell expressed, developmentally down-regulated 9) has been associated with the risk of developing Parkinson's disease and late-onset Alzheimer's disease, a disorder whose pathogenesis is modulated by cholesterol levels and cholesterol-related genes." (PMID 23468652, 2013). "In this article, we first introduce the pathological features of Alzheimer's disease, and describe recent data linking NEDD9, CASS4, and PTK2B to this syndrome." (PMID 25594051, 2014). "In summary, this study we have also identified important genes (NRG1, NEDD9, IRF5, IFI35, STAT1, STAT2, JAK2, IL3RA), and alterations in biological processes and pathways that may be associated with Alzheimer’s Disease." (PMID 34484988, 2021).
colon cancer (4 papers, 2012 to 2023). "NEDD9 has been evaluated in tumor progression in various tumor types including breast, lung, and colon cancers." (PMID 22984505, 2012).
esophageal squamous cell carcinoma (4 papers, 2021 to 2025). Esophageal squamous cell carcinoma (ESCC) is a type of esophageal carcinoma (EC) that can affect any part of the esophagus, but is usually located in the upper or middle third. "In esophageal squamous cell carcinoma, NEDD9 regulates CXCL8 to recruit MDSCs into tumors via the ERK pathway." (PMID 41368628, 2025). "In esophageal squamous cell carcinoma, MDSCs promote cancer cell stemness through NEDD9 via the Notch pathway." (PMID 41368628, 2025). "In esophageal squamous cell carcinoma (ESCC), MDSCs can activate NEDD9 to enhance cancer stemness with the involvement of Notch signaling." (PMID 36910604, 2023).
metastatic melanoma (4 papers, 2008 to 2019). A melanoma that has spread from its primary site to another anatomic site. "In the past six years, studies have identified elevated NEDD9 expression as contributing to cancer metastasis in multiple cancer types; it is an attractive biomarker of metastatic melanomas." (PMID 23226728, 2012). "Over-expression of LPXN [GenBank:NM_004811] and NEDD9 [GenBank:NM_006403] resulted in increased migration in the bone-derived metastatic prostate cancer cell line and in promotion of metastatic melanoma, respectively." (PMID 18928525, 2008). "To address this issue, we first performed comparative expression study of these factors on tissue sections from Chinese patients with benign melanocytic nevus, primary dermal and metastatic melanomas using antibodies specific for SOX9, SOX10, and NEDD9." (PMID 30642390, 2019).
renal cell carcinoma (4 papers, 2015 to 2021). "For example, the oncogenes of renal cell carcinoma, ANGPT2, and NEDD9, are the targets of miR-145, which is involved in tumor progression by suppression of the two oncogenes expression." (PMID 32404179, 2020).
triple-negative breast carcinoma (4 papers, 2011 to 2025). An invasive breast carcinoma which is negative for expression of estrogen receptor (ER), progesterone receptor (PR), and human epidermal growth factor receptor 2 (HER2). "NEDD9 expression was previously documented to correlate with poor prognosis in triple-negative breast cancers." (PMID 36831460, 2023). "Our group has previously reported the expression of NEDD9 in triple-negative breast cancers (TNBCs)." (PMID 36831460, 2023). "Analysis of NEDD9 expression across different cancers revealed an apparent correlation of this gene with the aggressive human triple-negative breast cancer." (PMID 21829474, 2011).
Arthritis (3 papers, 2016 to 2025). Inflammation of a joint. "This may be due to the effect of Nedd9 on other types of cells such as osteoblasts or osteocytes, or the effect of Nedd9 deficiency is only observed in mice under pathological conditions such as ovariectomy and arthritis, or those treated by TGF-ß." (PMID 27336669, 2016). "Moreover, knockout of NEDD9 attenuates collagen type II‐induced arthritis (CIA), indicating a protective role for NEDD9 deficiency in arthritis development." (PMID 37771106, 2023).
metastatic cancers (3 papers, 2011 to 2019). A carcinoma which has spread from the original site of growth to another anatomic site. "In particular, elevated NEDD9 expression is detected in a range of metastatic cancers and NEDD9 is considered to be a key pro-metastatic protein." (PMID 22509381, 2012). "NEDD9 (also known as HEF1 and CasL) is a pro-metastatic gene that is upregulated in different metastatic cancers." (PMID 31801619, 2019). "These discrepancies may probably be due to the fact that NEDD9 is required at early stages in the EMT process, but downregulated after the metastatic cancers undergo a reverse mesenchymal-epithelial transition (MET) process." (PMID 21829474, 2011).
viral infection (3 papers, 2006 to 2025). "In summary, although there are no direct studies elucidating the role of NEDD9 in viruses, it can be seen from the potential association of NEDD9 in a variety of diseases and COVID-19 that NEDD9 may play a potential role in the development of diseases caused by viral infection." (PMID 40266966, 2025). "Only in the context of viral infection with human T-cell leukemia/lymphoma virus and interaction with oncogenic TAX protein NEDD9 was found to be upregulated and linked to oncogenesis." (PMID 40506423, 2025). "Lack of depth in mechanistic research: although miR-18a-5p has been confirmed to inhibit H5N1 viral replication by targeting NEDD9, the specific molecular mechanism of NEDD9 in viral infection has not been fully elucidated." (PMID 40266966, 2025).
bladder cancer (2 papers, 2014 to 2017). "By multivariate analysis NEDD9 and p38 protein expression levels and various clinicopathological features (gender, stage, grade, number of tumors, and regional lymph node involvement) were independent prognostic parameters of bladder cancer patients' outcome." (PMID 28194179, 2017).
breast tumors (2 papers, 2011 to 2021). "One excellent example of this is the targeting of NEDD9 as an AURKA stabilizer in ciliary disassembly to potentiate AURKA treatment in breast tumours." (PMID 33860332, 2021). "We showed that expression of NEDD9 was frequently upregulated in TNBC cell lines, and in aggressive breast tumors, especially in TNBC subtype." (PMID 21829474, 2011).
invasive ductal carcinoma (2 papers, 2023). "Analysis of paired samples in the Cancer Genome Atlas (TCGA) breast cohort showed a significant upregulation of the NEDD9 DNA copy number in invasive ductal carcinoma relative to normal breast tissues." (PMID 36604412, 2023). "When compared to a nonmalignant (NM) tissue, which includes normal adjacent tissue (NAT), hyperplasia and benign disease expression of NEDD9 increased from nonmalignant to invasive ductal carcinoma (IDC) and metastatic lesions (lymph node-Met/LN)." (PMID 36831460, 2023).
malignant glioma (2 papers, 2012 to 2024). A grade III or grade IV glioma arising from the central nervous system. "We found that NEDD9 is up-regulated in malignant gliomas and in GB-NS, where the over-expression of miR-145 leads to the down-regulation of NEDD9." (PMID 22869051, 2012).
neuroblastoma (2 papers, 2014 to 2015). Neuroblastoma (NB) is the most common solid, extracranial childhood tumor. "The NEDD9 promoter contains binding elements for the retinoic acid receptor (RAR) and RXR, and NEDD9 is induced by retinoic acid in neural crest cells and neuroblastoma cells." (PMID 25594051, 2014).
ovarian tumor (2 papers, 2023 to 2025). "Silencing NEDD9 has been shown to reduce STAT3 activation, thereby suppressing ovarian tumor growth." (PMID 40362444, 2025). "Therefore, we compared gene expression profiles of NEDD9‐negative and NEDD9‐positive cells using data sets of gene analysis of ovarian tumor cells from NEDD9 knockout mice and wilde‐type mice." (PMID 37771106, 2023).
Parkinson disease (2 papers, 2012 to 2013). A progressive degenerative disorder of the central nervous system characterized by loss of dopamine producing neurons in the substantia nigra and the presence of Lewy bodies in the substantia nigra and locus coeruleus. "Among the few genes which continued steady rise in placental expression until term, NR3C1 coding for glucocorticoid receptor has been implicated in rheumatism and the malfunction of NRCAM and NEDD9 is related to brain disorders such as autism, Alzheimer’s and Parkinson’s disease." (PMID 23145134, 2012).